F10 (coagulation factor X)
Description:
Factor Xa is a vitamin K-dependent glycoprotein that converts prothrombin to thrombin in the presence of factor Va, calcium and phospholipid during blood clotting. Factor Xa activates pro-inflammatory signaling pathways in a protease-activated receptor (PAR)-dependent manner. Up-regulates expression of protease-activated receptors (PARs) F2R, F2RL1 and F2RL2 in dermal microvascular endothelial cells. Triggers the production of pro-inflammatory cytokines, such as MCP-1/CCL2 and IL6, in cardiac fibroblasts and umbilical vein endothelial cells in PAR-1/F2R-dependent manner. Triggers the production of pro-inflammatory cytokines, such as MCP-1/CCL2, IL6, TNF/TNF, IL-1beta/IL1B, IL8/CXCL8 and IL18, in endothelial cells and atrial tissues. Induces expression of adhesion molecules, such as ICAM1, VCAM1 and SELE, in endothelial cells and atrial tissues. Increases expression of phosphorylated ERK1/2 in dermal microvascular endothelial cells and atrial tissues. Triggers activation of the transcription factor NF-kappa-B in dermal microvascular endothelial cells and atrial tissues. Activates pro-inflammatory and pro-fibrotic responses in dermal fibroblasts and enhances wound healing probably via PAR-2/F2RL1-dependent mechanism. Activates barrier protective signaling responses in endothelial cells in PAR-2/F2RL1-dependent manner; the activity depends on the cleavage of PAR-2/F2RL1 by factor Xa. Up-regulates expression of plasminogen activator inhibitor 1 (SERPINE1) in atrial tissues.
Synonyms: fX; FXA
Tractability: Small molecule: an approved drug acts on it; a structure with a bound ligand is known; a high-quality ligand is known; it has a binding pocket of medium quality; it belongs to a druggable protein family. Antibody: its Gene Ontology location is reachable by antibodies, with high confidence; UniProt places it where antibodies can reach, with medium confidence; UniProt predicts a signal peptide or a membrane-spanning region. PROTAC: a small molecule that binds it is known. Other modalities: an approved drug acts on it.
Target class: Serine protease; Enzyme; Serine protease PA clan; Serine protease S1A subfamily; Protease
Gene: Protein-coding gene on chromosome 13 (113,122,788 to 113,149,531, forward strand). Ensembl gene ENSG00000126218.
Subcellular location: Secreted
Pathways (Reactome):
Disease: Defective F9 variant does not activate FX; Defective cofactor function of FVIIIa variant; Defective factor IX causes thrombophilia
Hemostasis: Amplification and propagation of coagulation cascade; Initiation of coagulation cascade; Regulation of clotting cascade
Metabolism of proteins: Gamma-carboxylation of protein precursors; Removal of aminoterminal propeptides from gamma-carboxylated proteins; Transport of gamma-carboxylated protein precursors from the endoplasmic reticulum to the Golgi apparatus
Gene Ontology:
Molecular function: phospholipid binding; protein binding; serine-type endopeptidase activity; calcium ion binding
Biological process: positive regulation of TOR signaling; blood coagulation; positive regulation of cell migration; proteolysis
Cellular component: endoplasmic reticulum lumen; external side of plasma membrane; extracellular region; Golgi lumen; plasma membrane
Genetic constraint (gnomAD): Loss-of-function variants: 22 observed, 32.46 expected, observed/expected ratio (o/e) 0.68, 90% interval 0.48 to 0.97. The upper end of that interval is the gene's LOEUF score, 0.97, which puts it in group 4 of 6, group 1 being the genes least tolerant of losing a copy. Missense variants: 520 observed, 665.32 expected, observed/expected ratio (o/e) 0.78, 90% interval 0.73 to 0.84. Synonymous variants: 251 observed, 269.8 expected, observed/expected ratio (o/e) 0.93, 90% interval 0.84 to 1.03.
Gene-disease validity (ClinGen):
ClinGen rates the evidence that F10 causes each of these diseases.
congenital factor X deficiency (autosomal recessive): Definitive. Congenital factor X deficiency is an inherited bleeding disorder with a decreased antigen and/or activity of factor X (FX) and characterized by mild to severe bleeding symptoms.
Homologues: Orthologues: chimpanzee F10 (100% identical), chimpanzee F10 (96% identical), macaque F10 (94% identical), mouse F10 (75% identical), dog F10 (75% identical), rabbit F10 (74% identical), rat F10 (74% identical), pig F10 (72% identical), guinea pig F10 (67% identical), tropical clawed frog f10 (51% identical), zebrafish f10 (48% identical). Paralogues in human: F9 (41% identical), F7 (38% identical), C1R (24% identical), CFI (23% identical), HGFAC (23% identical), KLKB1 (23% identical), F12 (23% identical), F11 (23% identical), C1S (21% identical), C1RL (20% identical), PRSS55 (18% identical), HP (16% identical), and 4 more.